EREG (epiregulin)
Diseases named in the same sentence as EREG in open-access papers (continued):
Sharing a sentence is not in itself a finding about the gene and the disease.
tumor (continued). "Increased levels of EREG activate EGFR downstream pathways and synergistically enhance IL-6/STAT3 signaling in malignant tumor progression." (PMID 34884633, 2021). "Among them, DPY30, EREG, PLA2G16, ZNF185, PADI1, INPP4B and AP1S3 have been reported to be involved in tumor genesis and progression, and they were significantly positively correlated with risk score." (PMID 34090418, 2021). "Collectively, EREG overexpression results in CSC properties and plays a critical role in metastasis during tumor progression." (PMID 34884633, 2021). "AREG and EREG are required for autocrine EGFR signaling, indicating that EREG plays an important role in tumor progression." (PMID 32596278, 2020). "After comparing the scores of mRNAsi and EREG-mRNAsi between the normal and tumor tissues of CRC patients, we found that mRNAsi and EREG-mRNAsi were both significantly higher in the tumor samples (P < 0.001)." (PMID 33134313, 2020). "Epiregulin (EREG), which is mainly secreted by fibroblasts, is a member of the epidermal growth factor (EGF) family of peptide growth factors and promotes tumor development, migration and invasion." (PMID 31234944, 2019). "Using RT-qPCR-based gene expression assays on RNA extracted from the 98 tumor samples, we found a statistically significant higher expression of both AREG and EREG in the basal tumors (ANOVA p < 0.001)." (PMID 31181806, 2019). "Patients and Methods: Formalin-fixed paraffin-embedded (FFPE) tumor samples from surgically removed primaries of the AIO KRK-0207 trial have been tested for AREG and EREG expression." (PMID 30467535, 2018). "Out of 371 tumor samples, 331 had measurable AREG and EREG expression levels (see CONSORT diagram for all subgroups)." (PMID 30467535, 2018). "EREG and AREG levels have been shown to predict tumor response and disease control in patients treated with EGFR-antibodies in both, RAS or KRAS exon 2 wild-type populations." (PMID 30467535, 2018). "The expression of HB-EGF, epiregulin, and phosphorylated EGFR (1068 and 1173) were undetectable in tumour sections in this study." (PMID 28032593, 2017). "Gene knock-down approaches using shRNA-based strategies were used to determine the requirement of EREG for growth of MCF10DCIS cells in vivo, and for identifying mechanisms through which EREG promotes tumor cell survival." (PMID 26215578, 2015). "Published microarray studies of early breast lesions, specifically hyperplastic enlarged lobular units, identified both AREG and EREG as genes that were significantly induced in these lesions." (PMID 26215578, 2015). "The actual mean intensity expression analysis in the clinical prostate database showed that AREG, EREG, and TGFA levels increased in metastatic tumor samples." (PMID 25004126, 2014). "Tumor tissues were stained by immunohistochemistry for VEGF-C, VEGF-D, VEGFR-3, Hif-1 α, PTEN, AREG and EREG expression and evaluated by two independent, blinded investigators." (PMID 25272957, 2014). "Considering all the patients showing downregulation of total HER4 in their tumor tissue, in 82% of these NRG4 was also downregulation and in 86% one or more of the EGFR-shared ligands (HB-EGF, epiregulin, betacellulin) was upregulated." (PMID 24728052, 2014). "At protein level, however, priming resulted in co-secretion of EREG and OSM by PBMC, while tumor-primed MΦ co-secreted HB-EGF and OSM in vitro." (PMID 23597096, 2013). "Although EGFR mRNA expression showed a relatively strong correlation between the primary tumor and metastases, the correlations of AREG and EREG, which are the ligands of the EGFR family, between primary and metastases were weaker than that." (PMID 22409860, 2012). "Western blot analysis was used to confirm the reduced protein expression of AREG, EREG and DUSP6 in A431 tumour cells stably transduced with AREG-, EREG-, and DUSP6-short hairpin (sh)RNAs." (PMID 22491422, 2012).
tumor (continued). "Wnt5a, expressed by inflammatory fibroblasts under hypoxic conditions, reinforces tumor angiogenesis suppression through VEGFR1 (Flt1)-dependent pathways and sustains a hypoxic niche that drives epiregulin production thereby potentiating tumor growth and metastasis." (PMID 41403952, 2025). "AREG, EREG, and VEGFA are angiogenesis-related and often overexpressed in tumor cells." (PMID 40501071, 2025). "Nevertheless, AREG/EREG expression may offer further refinement in selecting candidates for anti-EGFR therapy both in distal and proximal tumor locations and should be evaluated together with genomic negative hyperselection." (PMID 41167084, 2025). "Ultimately, increased EREG and AREG from any source may confer resistance by outcompeting EGFR-targeted mAbs for EGFR binding, thus re-activating EGFR and promoting tumor growth even in the presence of EGFR-targeted mAbs." (PMID 40727266, 2024). "Our data demonstrated that EREG acts as a mediator for cellular interactions between HCC and activated HSCs to accelerate HCC development by inducing cancer cell proliferation, migration/invasion, and tumor neovascularization during stimulation with LPS." (PMID 38673992, 2024). "Furthermore, increased EREG expression confers therapeutic resistance involving the epithelial–mesenchymal transition (EMT), cancer stemness, and tumor immune evasion." (PMID 38398101, 2024). "Epiregulin (EREG), is a core tumor immune biomarker in CuAS." (PMID 39482784, 2024). "EREG (−/−) mice have significantly lower levels of inflammation (macrophages, polynucleated leukocytes, and CXCL1) compared to wildtype mice, as well as significantly reduced tumor incidence." (PMID 38334792, 2024). "Epiregulin (EREG), a member of the epidermal growth factor family, combines with ErbB receptors and further contributes to proliferation, inflammation and anti-apoptosis in tumor cells." (PMID 37077811, 2023). "For the prognostic role of tumor EREG/AREG expression in RAS wt patients, no prognostic effect of high versus low expresser status on PFS or OS was seen in the subgroup treated with irinotecan alone." (PMID 37974093, 2023). "Contrasting to placebo, MIT treatment resulted in markedly reduced tumor sizes regardless of EREG expression in PSC27 cells, thus validating the efficacy of MIT as a cytotoxic agent." (PMID 36202915, 2022). "Many studies have shown that CXC chemokines attract neutrophils to tumor tissues, promote neovascularization, enhance the expression of pro-metastatic genes (e.g., SPARC, CXCR4, PTGS2/COX2, ANGPT, ALDH, EREG, and EFEMP), and thereby produce a pro-metastatic microenvironment." (PMID 36612163, 2022). "Cluster 0 (THBS1+MHClow TAMs) was prevalent in liver, with high expression of THBS1, MARCO and genes promoting the proliferation of EPCs and angiogenesis, such as EREG, AREG, and VEGFA, which could stimulate tumor growth and progression." (PMID 34489408, 2021). "KAP1 overexpression activates EREG, COX2, and MMPs, that stimulated tumor cell proliferation." (PMID 34884633, 2021). "A significant negative correlation was identified between EREG expression and tumor regression (r = −0.6, p < 0.001)." (PMID 32674321, 2020). "As CAFs function similarly to myofibroblasts in wound healing, we hypothesized that EREG might participate in the transition of NFs to the CAF phenotype from the very start of NF activation, thus promoting tumor progression." (PMID 31234944, 2019). "In the “tumor only” setting, the most differentially upregulated genes in EVP were related to its paracrine function such as Gdf6, a member of the TGFβa agonist, Wnt16, epiregulin, and neuroregulin." (PMID 30604758, 2019). "In tumor cells treated with PGE2 for 60 min the levels of AREG and EREG increased, whereas in the presence of c-SRC inhibitors (PP1 or SU6656) or ADAM-MMPs inhibitor (GM6001), AREG and EREG levels declined towards the baseline." (PMID 28415726, 2017).
tumor (continued). "Finally, the levels of EREG and HOXB9 were examined in the matched tumor and non-tumor tissues of CRC patients." (PMID 29199273, 2017). "Tumor genotype was established using Sequenom Mass ARRAY; EGFR, PTEN, cMET and AXL expression was assessed by immunohistochemistry, circulating markers of EGFR activation (TGF-α, amphiregulin, epiregulin, EGFR ECD) by ELISA and EGFR, MET copy number by FISH." (PMID 27028852, 2016). "EGFR receptors include AR, EGF, TGF-α, epiregulin, heparin-binding EGF (HB-EGF) and Hepatocarcinoma cell-derived hepatoma-derived growth factor (HDGF), have been confirmed to mediate tumorigenesis and promote tumor progression." (PMID 26451607, 2015). "Patients with negative AREG and EREG expression on their tumor had a significant longer DFS in comparison to AREG/EREG positive ones (p< 0.05)." (PMID 25272957, 2014). "The expression levels of EREG in the tumours of responding and non-responding patients by KRAS gene status is depicted in a waterfall plot." (PMID 23374602, 2013). "We acknowledge that specific knockdown of AREG or EREG expression failed to completely prevent Ctx-induced inhibition of tumour cell growth and survival." (PMID 22491422, 2012). "It is thought that elevated expression of epiregulin and/or amphiregulin may stimulate an autocrine loop through EGFR thus promoting tumor growth and survival." (PMID 24212785, 2011). "Similarly, several studies have reported an increased efficacy of cetuximab treatment of CRC patients, whose tumour had the WT K-RAS gene and expressed high levels of amphiregulin and/or epiregulin." (PMID 21750552, 2011). "The EGFR ligand epiregulin, COX2, and the matrix metalloproteinases 1 and 2 collectively facilitate tumor cell entry into the bloodstream and the breaching of lung capillaries by circulating tumor cells to seed lung metastases." (PMID 21914172, 2011). "We discovered that chemotherapy reshaped the tumor immune microenvironment, evident through the reduction in human leukocyte antigen (HLA) diversity and the increase in PDCD1/CD274 in CD8_ANXA1, LAMP3+ dendritic cell (DC_LAMP3), and EREG+ monocytes (mono_EREG)." (PMID 40725006, 2025). "Therefore, tumor cells destroy the normal connection of vascular endothelium by secreting protein angiopoietin-like 4 (Angptl4) and various cytokines, such as cyclooxygenase-2 (COX-2), epiregulin (EREG), and MMP-1/2, thereby promoting the extravasation of tumor cells." (PMID 40356596, 2025). "Furthermore, to enhance our validation, we analyzed eight pairs of CRC tissue samples and discovered that FXR levels were notably reduced in tumor tissues compared to adjacent non-cancerous tissues, whereas EREG levels were higher in the tumor tissues." (PMID 39834394, 2024). "Furthermore, we investigated the role of EREG on LPS-induced tumor cell proliferation; we measured the cell proliferation rate of Huh7 cells co-cultured with LX-2 cells treated with/without anti-EREG antibodies under LPS stimulation." (PMID 38673992, 2024). "However, EREG and AREG overexpression have still been observed across patient tumors regardless of KRAS BRAF mutational status and primary tumor location." (PMID 40727266, 2024). "Moreover, CellChat analysis unveiled ligand-receptor pairs mediating communication between tumor epithelial cells and disulfidptosis-related TME subgroups, such as TNFSF12-TNFRSF12A, TNF-TNFRSF1A, OSM-(OSMR+IL6ST), OSM-(LIFR+IL6ST), HBEGF-EGFR, and EREG-EGFR." (PMID 38292868, 2024). "In line with this study, we observed that HNSCC tumor cells expressing caveolin-1 could use EREG silencing, but not AREG silencing, to overcome oncogenic dependence on EGFR and develop resistance to CTX/irradiation combination therapy." (PMID 36899869, 2023). "While tumour RAS status is undoubtedly a valuable predictive marker for response to EGFRIs, it remains important to investigate the roles of other potential biomarkers that could improve patient selection (e.g. epiregulin/amphiregulin, PIK3CA, PTEN)." (PMID 28424871, 2017).
tumor (continued). "In addition, vascular remodeling factors, including epiregulin, cyclooxygenase 2 (COX2), MMP1, and MMP2, can promote breast cancer lung metastasis through facilitating the release of tumor cells into the circulation system and breaching lung capillaries by circulating tumor cells." (PMID 28356139, 2017). "The EGFR ligands: epidermal growth factor (EGF), transforming growth factor-α (TGFA), heparin-binding EGF-like growth factor (HBEGF), amphiregulin (AREG), beta-cellulin (BTC), epiregulin (EREG) and epigen (EPGN), may increase tumor growth, invasion, and metastasis through EGFR activation." (PMID 27669890, 2016). "Interestingly, the significance of EREG as a prognostic biomarker, which was observed in this study, was seen only on expression from the primary tumor, not on expression from the liver metastases." (PMID 22409860, 2012). "Comprehensive analysis revealed that the LRGs and its core genes showed positive correlations with DNAss, EREG-METHss, DMPss, ENHss, and EREG-EXPss, but negative correlation with RNAss, suggesting that the LRGs may promote tumor cell dedifferentiation and enhance stemness." (PMID 41035644, 2025). "We hypothesize that epiregulin (EREG), an epidermal growth factor (EGF) family member derived from hepatic stellate cells (HSCs) and activated by LPS stimulation, is a crucial mediator of HCC progression with epidermal growth factor receptor (EGFR) expression in the tumor microenvironment." (PMID 38673992, 2024). "Thus, the elevated EREG expression in TSC tumor cells was not accounted for by the EGFR signaling." (PMID 24748662, 2014). "The results showed that, in the TCGA cohort, C12orf56 and RORC had higher expression in normal samples, while EREG, INHBB, MAGEA12, and MMP10 had higher expression in tumor samples; ASRGL1 showed no expression difference between normal and tumor samples." (PMID 39883700, 2025). "The top negative DEGs, including ABCB1, SPRY1, EREG, PIK3R1, SPTBN1, VIM, KDR, and others, exhibit a negative correlation with tumor purity while demonstrating a strong positive correlation with T‐cell infiltration, especially CD8+ T cells." (PMID 40567015, 2025). "Together, Phd2 deficiency in hematopoietic cells (including TAMs), but importantly not in IECs, promotes CAC tumor growth at least in part by activation of the STAT3 and ERK1/2 signaling pathways mediated by EREG." (PMID 36509284, 2022). "However, our findings showed that the chemo-drugs led to increased EREG expression in NSCLC cells, which indicated that chemo-drug-induced acquired resistance might be attributed to EREG autocrine expression from tumor cells themselves, rather than a paracrine effect." (PMID 35551652, 2022). "As with EREG, a significant negative correlation was observed between AREG mRNA expression levels and tumor regression (r2 = −0.6, p < 0.001)." (PMID 32674321, 2020). "Since CaSR activation on tumor cells promotes the secretion of PTHrP, which is also known to block OPG production, the fact that the neutralizing antibody targeting epiregulin does not totally block CaSR-mediated decrease in OPG expression is not surprising." (PMID 28915604, 2017). "EREG was found to significantly enhance survival of non-transformed epithelial cells, leading to a possible model in which high levels of EREG in the developing tumor microenvironment may enhance tumorigenic properties of surrounding normal epithelium in a paracrine manner." (PMID 26215578, 2015). "However, analysis of matched primary tumor and liver metastases showed EREG and AREG expression levels were not significantly different between the two tumor sites." (PMID 40727266, 2024).
cancer (122 papers, 2008 to 2025). A tumor composed of atypical neoplastic, often pleomorphic cells that invade other tissues. "Abnormal epiregulin levels are associated with several diseases, including cancers and inflammatory conditions, making it a valuable subject of ongoing research to explore its potential as a biomarker and therapeutic target." (PMID 40638469, 2025). "Dysregulated epiregulin activity has been linked to various cancers, including those of the colon, liver, breast, lung, bladder, stomach, head, and neck." (PMID 40638469, 2025). "In recent years, the dysregulation of EREG expression has been implicated in several diseases, including cancer, inflammation, and tissue remodeling." (PMID 38673992, 2024). "JAK2/STAT3 signaling activates epiregulin-induced cancer-associated fibroblasts, which stimulates the epithelial–mesenchymal transition (EMT) of OSCC cells, which is necessary for migration and invasion." (PMID 38259290, 2023). "EREG was shown to increase stemness-associated genes expression and promoted cancer stem cells’ resistance to chemo-drugs via ERK signaling." (PMID 35551652, 2022). "EREG overexpression in normal fibroblasts mediated the cancer-associated phenotype, which promoted EMT through JAK2/STAT3 and IL-6 signaling pathways." (PMID 34884633, 2021). "EREG is up-regulated in carcinoma cell lines and is associated to the progression of breast, bladder and pancreatic carcinomas." (PMID 24330607, 2013). "Increased expression of EREG was associated to carcinoma growth, invasion and angiogenesis and correlated with poor prognosis." (PMID 24330607, 2013). "EREG is involved with various biological processes but may also be associated with promoting cancers in various tissues." (PMID 37854252, 2023). "Although Ereg knockout mice do not show any overt developmental phenotypes, Epiregulin has been implicated in the regulation of cell proliferation, differentiation, and cell death in multiple contexts, such as angiogenesis, skin inflammation, ovarian follicle formation, and cancer." (PMID 38514807, 2024). "As EREG is subject to frequent mutation, amplification and deep deletion as suggested by the TCGA pan-cancer atlas studies which document global genomics data, this factor has been considered an important predictor of disease progression in treatment-naïve patients of multiple cancer types." (PMID 36202915, 2022). "Interestingly, whilst the transcript level of certain genes shifted in a common direction across both clones, including ANKRD17 (down), BTC (up) and MTHFD2C (up), transcript level of the EREG gene, well characterised to be associated with numerous cancers, diverged between clones F and A5." (PMID 34432858, 2021). "The IH-induced increases of IL-6 and epiregulin in VSMCs, therefore, let us speculate that IH also causes an increase of IL-6 and epiregulin, and consequently, chronic inflammation in other smooth muscle tissues, resulting in the progression of several cancers." (PMID 31159449, 2019). "EREG is a known ligand for the epidermal growth factor receptor (EGFR), and its overexpression has been implicated in promoting proliferation in various cancers." (PMID 40970086, 2025). "In the MI group, we detected significant interactions between macro-C3-SPP1 and MHC-II+ cancer cells via the EREG/ERBB4 axis, which activates downstream MEK/ERK and PI3K/AKT signalling pathways, promoting cell proliferation and survival." (PMID 41281745, 2025). "Our findings of EREG involvement in ARSI-driven ferroptosis resistance extend previous research that has highlighted EREG's role in other cancer types." (PMID 39744439, 2025). "EREG also showed an increase in the cell migration and invasion of cancer cell lines with the abundant expression of EGFR in our study." (PMID 38673992, 2024). "Accumulating evidence has uncovered the overexpression of EREG in various human cancers, including NSCLC." (PMID 38398101, 2024).